S100A9 (S100 calcium binding protein A9)
Diseases named in the same sentence as S100A9 in open-access papers (continued):
Sharing a sentence is not in itself a finding about the gene and the disease.
colon carcinoma (30 papers, 2011 to 2024). "Overexpression of S100A8/S100A9 in mouse colon cancer cells CT26.WT led to differential increases in the secretion levels of various cytokines (CXCL5, CXCL11, GM-CSF, G-CSF, IL1a, IL1b, sTNF RI, and CCL3)." (PMID 38817853, 2024). "Transfection of S100A8 or S100A9 expression vectors into colon cancer cells significantly activated NF-κB, STAT3, and ERK-MAPK, highlighting the role of S100A8/A9 as potent cancer promoters by orchestrating key connections within the signaling cascade." (PMID 38817853, 2024). "Our analysis revealed significant upregulation of S100A8 and S100A9 in colon cancer tissues compared to normal intestinal mucosa in the GSE9438 dataset." (PMID 38817853, 2024). "The aim of this study was to elucidate the effects and potential mechanisms of high S100A8 and S100A9 expression in colon cancer cells on the secretion of inflammatory factors and malignant transformation of tumors." (PMID 38817853, 2024). "In colon cancer progression, S100a9 is oxidized by NOX1-produced ROS, which facilitates binding to mTORC1 and its activation." (PMID 37723445, 2023). "In colon cancer cells, S100a9 is oxidized by NOX1-produced ROS, which facilitates binding to mTORC1 and its activation." (PMID 37723445, 2023). "In fact, the tumor sphere formation ability was decreased, and the levels of a panel of established CSC markers, including CD133, CD44, Sox2, Oct4, Nanog, and ALDH1A1, were decreased in colon cancer cells treated with GM‐Exo subjected to S100A9 knockdown." (PMID 31559140, 2019). "Together, these results suggest that exosomal S100A9 from G‐MDSCs enhances the stemness of colon cancer cells." (PMID 31559140, 2019). "S100a9 was identified as a tumor specific protein marker in AOM-induced colon tumors by matrix-assisted laser desorption/ionization-mass spectrometry." (PMID 29326691, 2017). "Instead, S100A9 is known to induce NF-κB activity, and targeting NF-κB in colon cancer cells educates macrophages toward a M1-like phenotype and inhibits peritoneal metastasis." (PMID 26673090, 2015). "Additional markers, such as S100A9, have been described to identify monocytic MDSCs in humans with colon cancer and cross-reacting S100A9 proteins are available." (PMID 23110794, 2012). "However, in pancreatic cancer cells and colon cancer cells, S100a9 is located in the intracellular space and exerts an inhibitory effect on autophagy, which is similar to what was found in our research." (PMID 37723445, 2023). "However, the stemness characteristics of colon cancer cells were decreased when S100A9 was knocked down in hM‐Exo." (PMID 31559140, 2019). "Taking into account the roles of exosomal S100A9 from G‐MDSCs in promoting CRC cell stemness and tumorigenesis in CT‐26 cells and CAC mice, we observed whether human exosomal S100A9 from MDSCs had similar characteristics in human colon cancer cells." (PMID 31559140, 2019). "However, high levels of endogenous S100A9 can lead to oxidative stress-induced apoptosis, as shown by overexpression or high-dose stimulation of S100A9 in several cancer cells including colon cancer." (PMID 26431492, 2015). "RAGE has been proposed to serve as a primary receptor for S100 proteins in the extracellular space, and plays an important role in S100A8- or S100A9-induced proliferation and migration of prostate and breast and colon cancer cells involving the MAPK/NF-κB signaling." (PMID 23637971, 2013). "In addition, S100A8 and S100A9-activated colon cancer cells showed an upregulation of LCN2 gene expression compared to non-stimulated cells." (PMID 22559235, 2012). "Utilizing Western blotting, we examined three colon cancer cell lines (CT26, SW620, and SW480) that were genetically modified to overexpress S100A8 and S100A9." (PMID 38817853, 2024).
colon carcinoma (continued). "Under hypoxic conditions, granulocytic MDSC (G‐MDSC)‐derived exosomes carrying S100A9 proteins can promote cancer stemness in murine CT26 colon cancer cells and azoxymethane/dextran sodium sulfate (AOM/DSS)‐induced colon cancer." (PMID 37830387, 2023). "The binding of S100A8/S100A9 on RAGE and carboxylated glycan in colon cancer activates the NF-κB pathways, resulting in a life-threatening link between inflammation and cancer." (PMID 36613714, 2022). "In colon cancer, S100A8 and S100A9 induce RAGE- and carboxylated glycan-dependent phosphorylation of ERK1/2 and SAPK/JNK, but in prostate and breast cancer, they promote p38 phosphorylation." (PMID 36613714, 2022). "S100A8 and S100A9 proteins are also regarded as signals to recruit PMN and PMN-MDSC to pre-metastatic sites in colon cancer." (PMID 32153594, 2020). "We identified that BGN, S100A8, S100A9, and TNC expression levels were elevated significantly in colon cancer samples." (PMID 32050430, 2020). "Furthermore, S100a8 and S100a9 promoted colorectal tumorigenesis by recruiting macrophages, and promoting the proliferation and invasion of colon cancer cells, suggesting that the aberrant expression of S100a8 or S100a9 is linked to non-resolving inflammation and ultimately to carcinogenesis." (PMID 29326691, 2017). "To investigate the impact of elevated S100A8 and S100A9 expression on the secretion of inflammatory factors by colon cancer cells, we transfected CT26 colon cancer cells with overexpression plasmids containing S100A8 and mS100A9, both individually and in combination." (PMID 38817853, 2024). "In another study, LCN2 gene expression was upregulated in S100A8 and S100A9-stimulated colon cancer cells compared to non-stimulated cells." (PMID 34072157, 2021). "Furthermore, the phosphorylation levels of STAT3 and NF‐κB p65 were enhanced in GM‐Exo‐treated colon cancer cells, but the levels of p‐STAT3 and p‐p65 were decreased in GM‐Exo subjected to S100A9 knockdown." (PMID 31559140, 2019). "Mice lacking S100-A9 showed no obvious phenotype, they are viable und fertile, but in a mouse model of colon cancer they showed significantly reduced tumor incidence, growth and metastasis." (PMID 21760917, 2011). "However, anti-S100a9 Ab treatment did not trigger colon cancer cell apoptosis in vivo." (PMID 29326691, 2017). "The results showed that the expression levels of S100A9 and TNC in colon carcinoma tissues were not correlated with age or gender (P > 0.05), but correlated with TNM stages and metastasis (P < 0.05)." (PMID 27191989, 2016).
myocardial infarction (30 papers, 2008 to 2025). Gross necrosis of the myocardium, as a result of interruption of the blood supply to the area, as in coronary thrombosis. "S100a8 and S100a9 can also cause stent thrombosis in the very late stage of acute myocardial infarction." (PMID 35741040, 2022). "Previous research has shown that S100A9 plays a crucial role in inflammatory and reparative immune responses following myocardial infarction across various models." (PMID 40069854, 2025). "The small-molecule pharmacological inhibitor ABR-238901 selectively targets S100A9 and has demonstrated efficacy in reducing infarct size and enhancing cardiac function in preclinical models of myocardial infarction." (PMID 40948795, 2025). "The MMM/RNA NPs exhibited outstanding S100A9 silencing efficacy and demonstrated a robust capability to ameliorate myocardial infarction, owing to their superior biocompatibility." (PMID 39264262, 2024). "Consistently, treatment with recombinant NGAL induced reparative macrophages in neutrophil-depleted mice, whereas long-term S100A9 blockade recapitulated the deleterious actions of neutrophil depletion on recovery from myocardial infarction." (PMID 38189129, 2024). "Intravenous injection of MMM/RNA NPs significantly reduced S100A9 levels in serum and myocardial tissues, further decreasing myocardial infarction area and improving cardiac function." (PMID 39264262, 2024). "Based on an analysis of the scRNA-seq and mRNA-seq data of myocardial infarction mice, it has been found that S100a9 regulated autophagy through the MAPK and PI3K-AKT signaling pathways." (PMID 37723445, 2023). "We analyzed the expression levels of LILRB2, TLR2, NCF2, and S100A9 in AMI samples (blood samples on the first day of myocardial infarction) and stable coronary artery disease (CAD) controls." (PMID 34490057, 2021). "Nonetheless, accumulating data suggest that S100A9 exerts a functional role in several inflammatory conditions, including arthritis, myocardial infarction, endotoxin-induced lung injury and acute pancreatitis." (PMID 34884728, 2021). "However, the S100a9 inhibitor significantly reduced the myocardial infarction area after MIR and reduced the levels of myocardial injury markers." (PMID 38323308, 2024). "However, long-term S100a9 blockade negatively affects cardiac recovery in a murine myocardial infarction model." (PMID 37723445, 2023). "In addition to myocardial tissue, S100a8 and S100a9 are also highly expressed in the blood of patients with acute myocardial infarction." (PMID 35741040, 2022). "S100A8, S100A9 40, 41, and vimentin 42 are recognized as DAMPs in myocardial infarction (MI) and atherosclerosis." (PMID 35173530, 2022). "The present review will attempt to summarize the increasing body of evidence demonstrating the involvement of S100A8 and S100A9 in atherogenesis, plaque vulnerability, myocardial infarction (MI), and heart failure." (PMID 24453429, 2013). "Recent studies have demonstrated that circulating neutrophils were rapidly activated and recruited to the injured myocardium after myocardial infarction, releasing S100A8/S100A9 locally in the ischemic microenvironment." (PMID 38062310, 2025). "FCN1, CD14, S100A9, ALDH2, hsa-let-7d, hsa-let-7b, hsa-miR-124-3, and hsa-miR-9-1 were identified as potential candidate regulators in acute myocardial infarction." (PMID 30886860, 2019). "Increased plasma levels of S100A9 was a predictor for future nonfatal myocardial infarction among healthy women and S100A8/A9 heterocomplex was found to be an early marker for detection of acute coronary syndrome." (PMID 23209553, 2012). "Interestingly, our previous proteomics study predicted that the protein S100A9 appeared as an important target, and macrophage/microglial inflammation might be involved in the process of PCF improving depression induced by acute myocardial infarction (AMI)." (PMID 35814253, 2022).
myocardial infarction (continued). "Here, we found upregulation of S100A8, S100A9, and CEBPD in PBMCs of stable coronary artery disease/myocardial infarction (sCAD/MI) cases, compared against controls, together with a positive correlation of S100A8 and S100A9 expression with that of CEBPD in these cells." (PMID 35543413, 2022). "Six hub genes, including BCL3, HCK, PPIF, S100A9, SERPINA1, and TBC1D9B that differentiated on admission after myocardial infarction the HF patients from the non-HF ones, can serve as early prognostic biomarkers of post-AMI patients." (PMID 31850068, 2019). "Patients with acute myocardial infarction have elevated levels of S100A936 and it was shown in mice that absence of S100A9 leads to prolonged time to arterial occlusion." (PMID 28887518, 2017).
Arthritis (28 papers, 2009 to 2025). Inflammation of a joint. "Studies have implicated S100A8 and S100A9 in the initiation and progression of immunoinflammatory diseases, including autoimmune synovitis, Sjögren’s syndrome, arthritis, systemic sclerosis and systemic lupus erythematosus." (PMID 40346703, 2025). "Accordingly, S100A9 knockout (KO) mice exhibit decreased pathogenic outcomes in several mouse models of disease, such as sepsis, autoimmune disease or arthritis." (PMID 35543413, 2022). "Synovitis during RA is characterized by a high abundance of neutrophils and macrophages expressing S100A8 and S100A9 especially at the cartilage–pannus junctions indicating that S100-expression is closely associated with cartilage destruction and bone erosion in arthritis." (PMID 30828327, 2019). "Beyond that, S100A8 and S100A9 are known key players in the pathogenesis of arthritis in murine models." (PMID 35543413, 2022). "Accordingly, GSK-J4 treatment of our ER-Hoxb8 monocytes reduced expression of the proinflammatory alarmins S100a8 and S100a9, which have been shown to drive the inflammatory process of arthritis." (PMID 35543413, 2022). "Studies showed that two members of the S100 family, S100A8 and S100A9, are overexpressed at local sites of inflammation, which have been proven to be useful genes of inflammatory diseases such as arthritis, bowel disease, and chronic inflammatory lung." (PMID 34803684, 2021). "Functional relevance of S100A8/S100A9 expression was further confirmed by analysis of experimental models of arthritis and synovial inflammation in S100A9−/− mice." (PMID 30828327, 2019). "Preclinical models in mice have also confirmed a functional role of S100A8/S100A9 in the process of arthritis and autoimmunity." (PMID 30828327, 2019). "S100-alarmins, especially S100A8/S100A9, are highly upregulated in different forms of arthritis and autoimmune diseases in children." (PMID 30828327, 2019). "S100a9-/- mice have been found resistant to adjuvant-induced arthritis and systemic lupus erythematosus, the latter resistance being due at least in part to reduced CD8+ T cell activation." (PMID 31437241, 2019). "S100A8/S100A9 acts on different cell types and induces several molecular pathways highly relevant in the pathology of arthritis." (PMID 30828327, 2019). "The treatment of neutrophils with S100A9 enhances transendothelial migration, while blockage with anti-S100A9 antibodies diminishes leukocyte infiltration in the joints of a murine arthritis model." (PMID 29942307, 2018). "In a murine arthritis model, treatment with anti-S100A9 antibodies diminishes pro-inflammatory cytokine levels both in joints and in serum and preserves bone/collagen integrity." (PMID 29942307, 2018). "S100A9 expression, as depicted by optical imaging, showed excellent correlation with clinical scoring, clearly discriminating clinically mild from severe joint inflammation with a high signal-to-noise ratio (SNR) for severely inflamed joints." (PMID 25098555, 2014). "High extracellular concentrations of S100A8 and S100A9 are found in the serum and at inflammatory sites in autoimmune diseases including arthritis, lupus, and Crohn’s disease." (PMID 23977231, 2013). "Here, we have shown that S100A9 and calprotectin are detected early in serum after the induction of arthritis." (PMID 23029038, 2012). "Anti-S100A9 and anti-TNFα treatment significantly reduced the maximum arthritis score median, from 6.8 in the isotype control-treated group to 3 and 1.4 in groups treated with anti-S100A9 and anti-TNFα, respectively." (PMID 23029038, 2012). "In the present study, we have identified S100A9 as a key player in the initiation and progression of arthritis." (PMID 23029038, 2012). "In this study, we investigated the importance of S100A9 in RA by using neutralizing antibodies in a murine lipopolysaccharide-synchronized collagen-induced arthritis model." (PMID 23029038, 2012).
Arthritis (continued). "We therefore elected to specifically deplete S100A9 using an antibody to address the extracellular role of S100A9 in arthritis." (PMID 23029038, 2012). "Decreased arthritis score was recently reported in S100A9-null mice compared to wild-type animals in antigen-induced arthritis, while no significant impact of S100A9 gene deletion has been reported in the K/BxN arthritis model." (PMID 23029038, 2012). "Mice treated with anti-S100A9 showed markedly decreased arthritis severity scores compared to the isotype control group." (PMID 23029038, 2012). "Secretion of both IL-6 and TNFα was dose-dependent, with maximal secretion detected at 1 μg/ml of S100A9, a concentration found in the synovial fluid of arthritis patients." (PMID 23029038, 2012). "The expression of S100A8 and S100A9 was found to be strongest at the cartilage-pannus junction, which is the prime site of cartilage destruction and bone erosion in arthritis." (PMID 19710928, 2009). "In contrast, no change in TDS was observed in the S100a9−/− mice with SCW arthritis, underlining the role of S100A8/9 in pain perception." (PMID 32854769, 2020). "In addition, blocking S100A9 resulted in diminished TNFα and IL-6 expression in a collagen-induced arthritis model." (PMID 23977231, 2013). "In addition, recent studies have demonstrated a role for S100A9 in animal models of lupus, arthritis, and Alzheimer’s disease." (PMID 23977231, 2013). "We found that the mRNA expression levels of S100A9, S100A8, and MMP8 were significantly decreased after CFA-induced arthritis pain, while BoNT/A increased the expression changes of these genes." (PMID 34803684, 2021). "The results showed that the expression levels of S100A9, S100A8, and MMP8 in rats with arthritis pain were visibly lower than the Sham group." (PMID 34803684, 2021). "The identification of S100A9, S100A8, and MMP8 genes can provide new therapeutic targets for arthritis pain and affect the signaling pathway to play an anti-inflammatory role after the treatment of BoNT/A." (PMID 34803684, 2021). "Experimental arthritis is less severe in S100a9-/- mice (which lack S100A9 and S100A8/A9 proteins) and in mice receiving anti-S100A9 antibodies." (PMID 31437241, 2019). "Subsequently, regulation of these genes in DRG of S100a9−/− mice after induction of SCW arthritis was absent." (PMID 32854769, 2020). "First, we determined whether in the acute synovitis model of SCW induced arthritis in C57Bl/6 mice, S100A8 or S100A9 genes and proteins were expressed." (PMID 32854769, 2020). "Indeed, S100A9−/− mice, which also lack the S100A8 protein, show reduced bone erosion in antigen-induced arthritis through a mechanism partly related to a decrease in osteoclasts." (PMID 23029038, 2012). "Importantly, S100a8 and S100a9 were the top genes that distinguished the arthritis mice and non-arthritis mice on the day after infection." (PMID 37396347, 2023). "As expected, S100a9−/− and WT controls did not develop any macroscopically visible arthritis." (PMID 34412663, 2021). "We did on the other hand, however, also not observe an amelioration of the pathology in the absence of S100a9 as might be expected in the absence of a strong pro-inflammatory factor that has been shown to be involved in many experimental arthritis models." (PMID 34412663, 2021). "The lack of DRG inflammation in synovitis during acute SCW-induced arthritis refutes our hypothesis, derived from the DMM-data, that influx of cells or production of MCP-1 by the DRG would be responsible for the sensitization in both WT and S100a9−/− mice." (PMID 32854769, 2020). "Mediators for inflammation, except TNFα and IL-1, were increased in synovial washouts during SCW arthritis, but none of the inflammatory mediators (KC, MCP-1, IL-6) were significantly different between WT and S100a9−/−." (PMID 32854769, 2020).
Arthritis (continued). "In the present study, we show that the absence of S100a9 does not alter joint inflammation, cartilage destruction, and bone erosion in the ankle joints of Il1rn−/− mice, suggesting that S100A8/A9 is not essential for the development of arthritis in the presence of such excessive IL-1 signaling." (PMID 34412663, 2021).